ENSG00000250644 (novel protein)
Gene: Protein-coding gene on chromosome 11 (1,734,821 to 1,763,954, reverse strand). Ensembl gene ENSG00000250644.
Genetic constraint (gnomAD): Loss-of-function variants: 44 observed, 52.81 expected, observed/expected ratio (o/e) 0.83, 90% interval 0.65 to 1.07. Missense variants: 685 observed, 732.6 expected, observed/expected ratio (o/e) 0.94, 90% interval 0.88 to 1. Synonymous variants: 364 observed, 337.67 expected, observed/expected ratio (o/e) 1.08, 90% interval 0.99 to 1.18.